DSG3 (desmoglein 3)
Diseases named in the same sentence as DSG3 in open-access papers (continued):
Sharing a sentence is not in itself a finding about the gene and the disease.
pemphigus (continued). "Pemphigus is a rare group of autoimmune blistering disorders affecting the skin and mucous membranes, characterized by the formation of antibodies against cell surface adhesion molecules - specifically desmoglein 1 (Dsg1) and desmoglein 3 (Dsg3)." (PMID 40642697, 2025). "In desmosomes, the pemphigus autoantigens desmoglein 1 (Dsg1) and Dsg3 link adjacent cells." (PMID 39882246, 2024). "Other target molecules of epidermal adhesion are now identified in the pathogenesis of pemphigus, as well as mitochondrial proteins, cholinergic receptors, and other molecules, which act synergistically with anti-Dsg1 and Dsg3 antibodies in epidermal acantholysis." (PMID 38851894, 2024). "The active DSG3 pemphigus mouse model was successfully used in many studies." (PMID 37237515, 2023). "The usage of pemphigus mouse models was transformed by the development of Dsg3-/- knockout mice." (PMID 37180099, 2023). "Further characterization indicated that although an individual anti-Dsg3 IgG is not sufficient to cause acantholysis in adult mice, several clones together can induce a pemphigus phenotype." (PMID 37180099, 2023). "Moreover, FoxP3+CD25hiCD4+ T cells and DSG3-reactive IL-10+CD4+ T cells are reduced in blood from patients with pemphigus compared to healthy individuals." (PMID 37138879, 2023). "Pemphigus refers to a group of rare autoimmune blistering diseases characterized by autoantibodies targeting desmosomal cadherins: most commonly desmoglein-1 (Dsg1) and desmoglein-3 (Dsg3)." (PMID 35755063, 2022). "We show that blocking IgG binding on FcRn by efgartigimod, a recombinant Fc fragment undergoing clinical studies for pemphigus, stabilizes the keratinocyte monolayer, whereas the loss of desmoglein-3 is not prevented by efgartigimod." (PMID 35326398, 2022). "We found that ADAM10 inhibition is protective against the pathogenic effects of pemphigus autoantibodies which primarily target Dsg3 but not Dsg1." (PMID 35844545, 2022). "These antibodies are expressed and secreted by Dsg3 autoreactive B cells that are activated presumably by the autoreactive T cells, in which cytokines could also play an essential role in pemphigus disease pathophysiology." (PMID 35783635, 2022). "In pemphigus patient skin, Dsg1 and Dsg3 immunostaining was altered especially along blister edges." (PMID 35711465, 2022). "The function of nonjunctional DSG3 remains not fully understood; however, it was thought that it is associated with cell signalling and is the primary target of pemphigus IgG." (PMID 35000271, 2022). "Further, a significant drop in autoantibody titers between pemphigus diagnosis and the first 12 months of follow-up occurred in the vast majority of patients with PV (83.6% and 87.1% for anti-Dsg1 and anti-Dsg3, respectively) and PF (94.4% and 83.3% for anti-Dsg1 and anti-Dsg3, respectively)." (PMID 35880183, 2022). "To test whether the protective effect of ADAM10 inhibition depends on the amount of autoantibodies targeting Dsg3, we performed dissociation assays with AK23, a pathogenic monoclonal Dsg3 autoantibody derived from a pemphigus mouse model." (PMID 35844545, 2022). "Moreover, expression of CD154 on CD4+ T cells correlated positively with Dsg3 titers in pemphigus patients as shown by Spearman rank correlation (correlation coefficient 0.4634, p= 0.0197)." (PMID 36203615, 2022). "Previous studies have shown that IgG and IgA antibodies in patients with IgG/IgA pemphigus could target Dsg1, Dsg3, and/or desmocollin 1 (Dsc1)–Dsc3 to a different extent, which may account for the mixed clinical presentations of the disease." (PMID 35625932, 2022). "The Desmoglein Compensation Hypothesis is an elegant theory that attempts to explain lesion morphology of pemphigus patients based on anti-Dsg3/1 antibody profiles." (PMID 36211362, 2022).
pemphigus (continued). "Although Dsg-specific autoantibody titre was long-thought to correlate with disease activity in pemphigus, more recent studies have detected anti-Dsg3 IgG antibodies in patients who were in clinical remission, suggesting the existence of non-pathogenic Dsg-specific IgG." (PMID 35187073, 2021). "Additionally, in pemphigus, excessive ROS impel the oxidative modification of proteins such as Dsg1 and Dsg3 that stimulate the immune system to produce autoantibodies and cause acantholysis." (PMID 34355664, 2021). "Studies on direct inhibition of Dsg1 and Dsg3 interaction in pemphigus." (PMID 34434944, 2021). "The hypothesis that the signalling pattern orchestrated by Dsg1 and Dsg3 in pemphigus are to some extent different also helps to explain why blister formation in pemphigus requires antibodies against Dsg1." (PMID 34434944, 2021). "In addition to indirect roles of T cells in the pathogenesis of pemphigus, direct recognition of anti-Dsg3 by Dsg3-specific CD4+ T helper cells has been suggested." (PMID 33954018, 2021). "Moreover, high concentrations of Dsg3-reactive IgE and intercellular IgE deposits in pemphigus vulgaris patients have been reported, further supporting the involvement of mast cells in pemphigus." (PMID 34660634, 2021). "However, AK23, which is a Dsg3-specific antibody from an active mouse model, and monoclonal autoantibodies targeting Dsg1 isolated from PF patients have been shown to induce pemphigus-typical acantholysis." (PMID 34434944, 2021). "Other actin binding proteins such as cortactin, which have been shown to be involved in pemphigus pathogenesis, also bind to extra-desmosomal Dsg3 and thus may participate in desmosome assembly." (PMID 34434944, 2021). "In pemphigus in particular, the high efficacy of rituximab, the dramatic reduction of anti-Dsg1/anti-Dsg3 serum levels following rituximab, and the correlation of these autoantibodies with clinical response indicate that short-lived plasma cells are the main source of autoantibodies in this disease." (PMID 34068035, 2021). "Similarly, our understanding of immune-pathogenesis is almost completely restricted to Dsg3 as the target autoantigen, despite knowledge from human patients that this is only one part of the pemphigus picture." (PMID 35187073, 2021). "Because Src was no longer activated after 24 h and Src inhibition was only protective during timeframes when Src was active, it can be assumed that Src plays a less central role in pemphigus pathogenesis and likely contributes during the initial phase only when the extradesmosomal Dsg3 is depleted." (PMID 34434944, 2021). "Next, experimental pemphigus was induced in mice by transfer of Dsg3-hybridoma cell lines." (PMID 33505392, 2020). "In pemphigus patients, CD19+ B cells and CD138+ PCs were found to be significantly increased in lesional skin and these isolated lymphocytes produced pathogenic anti-Dsg1 and anti-Dsg3 antibodies in vitro." (PMID 33297481, 2020). "Pemphigus is an organ-specific autoimmune bullous disease characterized by keratinocyte detachment, resulting from the presence of autoantibodies targeting 2 major desmoglein (Dsg) proteins, Dsg1 and Dsg3, approximately 160 and 130 kDa, respectively." (PMID 33108348, 2020). "In contrast, increased bond lifetime of the heterophilic Dsg2-Dsg3 interactions may stabilize keratinocyte adhesion under conditions when Dsg3-mediated cell adhesion is disturbed by pemphigus autoantibodies." (PMID 33193387, 2020). "In addition, activation of ERK1/2 is also involved in the pathogenesis of pemphigus, an autoimmune blistering skin disease caused by autoantibodies against DSG1 and DSG3." (PMID 32556797, 2020). "Anti-Dsg1 and anti-Dsg3 antibodies are both well-studied markers for pemphigus." (PMID 33129291, 2020). "In pemphigus, cAMP levels increase following IgG binding to Dsg3." (PMID 33193415, 2020).
pemphigus (continued). "In fact, besides Dsg3 and Dsg1, other non-desmoglein autoAbs, either pathogenic or non-pathogenic, have been identified in pemphigus patients." (PMID 31275324, 2019). "In conclusion, we have developed an adult DSC3 pemphigus mouse model that differs from the DSG3 model and supports the concept that antigens other than desmogleins may be responsible for different phenotypes in human pemphigus." (PMID 31275323, 2019). "It remains unclear what initial trigger activates these precursors, although it is possible that molecular mimicry may drive initial responses against Dsg3, which is also a mechanism proposed for the related endemic form of pemphigus, fogo selvagem." (PMID 31340153, 2019). "Therefore, it is important to characterize the role and mechanisms of autoantibodies targeting Dsg3 in pemphigus." (PMID 31178865, 2019). "In Australia, the process of diagnosing pemphigus involves typical physical findings, histopathology, direct immunofluorescence (DIF), indirect immunofluorescence (IIF), and enzyme-linked immunosorbent assay (ELISA) testing to Dsg1 and Dsg3." (PMID 29872685, 2018). "In the study presented here we show that keratins regulate the binding properties of Dsg1 and Dsg3, which are the major antigens in pemphigus, and propose a new concept how keratins could directly influence desmosomal adhesion." (PMID 29616033, 2018). "Furthermore, p38MAPK, a central molecule deregulated in pemphigus, was shown to be essential for Dsg3 internalization as well as for the KIF network alterations in response to PV-IgG treatment." (PMID 29922278, 2018). "However, several IGAD cases showed clear acantholytic histology, suggesting that IgG antibodies to Dsg1 and/or Dsg3 induced the cell detachment similar to IgG-type pemphigus." (PMID 29867971, 2018). "The rather simple explanation of pemphigus’ pathogenesis through steric hindrance relies on the DSG compensation hypothesis, which states that the distribution of DSG1 and DSG3 in the epidermis determines the site of blistering in pemphigus skin." (PMID 28928733, 2017). "Induction of altered signaling: antibodies against desmoglein-3 in pemphigus." (PMID 28620373, 2017). "The dogma that pemphigus is caused by keratinocyte dissociation (acantholysis) as a distinctive and direct consequence of the presence of autoAb targeting two main proteins of the desmosome—desmoglein (DSG) 1 and/or DSG3—has been put to the test." (PMID 28928733, 2017). "After stimulation with Dsg3 we could identify autoreactive IL-21-secreting cells in 50% of the pemphigus patients." (PMID 26872212, 2016). "Therefore we stimulated PBMC from pemphigus patients and HC with Dsg3 protein ex vivo and analyzed the number of IL-21-secreting cells by ELISpot assay." (PMID 26872212, 2016). "Next, we were interested whether Dsg3-specific IL-21-secreting T cells would contribute to the observed elevated IL-21 plasma levels in pemphigus." (PMID 26872212, 2016). "Following the strong correlation of the IL-27 concentrations with anti-Dsg3 IgG titers, we next addressed the question how the auto-ab production in pemphigus could be mediated by IL-27." (PMID 26872212, 2016). "Moreover, we identified Dsg3-specific IL-21-producing cells in a significantly higher number in the analyzed pemphigus patients compared to HC by ELISpot assay." (PMID 26872212, 2016). "Pemphigus is a devastating autoimmune blistering disease mediated by autoantibodies directed against keratinocyte adhesion molecules, desmoglein (Dsg3 and Dsg1), which when targeted lose their cellular adhesion properties and separate from one another to form blisters in the skin and oral cavity." (PMID 24900992, 2014). "Here, we applied a monoclonal Dsg2 antibody (mAb) targeting the extracellular domain which we have shown to be inhibitory in a previous study as well as AK23, an inhibitory monoclonal antibody from an active pemphigus mouse model targeting the Dsg3 adhesive interface." (PMID 23326495, 2013).
pemphigus (continued). "However, conflicting models for pemphigus pathogenicity have arisen from studies using either polyclonal PV patient IgG or monoclonal Dsg3 antibodies." (PMID 23226536, 2012). "The first evidence that keratinocyte antigens other than Dsg 1 and 3 are pathophysiologically relevant in pemphigus was provided by experiments showing the ability to induce suprabasal acantholysis and gross skin blisters in Dsg3 neonates by passive transfer of PV patients’ antibodies." (PMID 21939410, 2012). "The transference of autoantibodies was also reported in neonatal pemphigus, which is characterized as a rare transitory autoimmune blistering disease caused by transfer of maternal IgG autoantibodies specific for desmoglein 3 to the neonate when the mother is affected with pemphigus." (PMID 22235228, 2012). "However, as proven in two recent reports, these findings with these Dsg3 recombinants are valid and show differential reactivity against distinct portions of the Dsg3 ectodomain in different pemphigus patients and different diseases stages." (PMID 20671975, 2010). "Pemphigus is a chronic mucocutaneous autoimmune bullous disease, characterized by the presence of autoantibodies against the desmosomal cadherins, desmoglein 1 (Dsg1), and/or desmoglein 3 (Dsg3)." (PMID 20585596, 2010). "Additionally, IgG against several non-Dsg3 proteins, such as desmocollin 3, has been detected in pemphigus patients, raising speculation of potential synergic effects eventually triggering acantholysis." (PMID 37174740, 2023). "In addition to Dsg3 and/or Dsg1 auto-abs, IgG auto-abs against several target proteins other than Dsgs such as desmocollin 3 were identified in pemphigus patients, raising speculations about potential synergic effects eventually triggering acantholysis." (PMID 37180099, 2023). "Additionally, experimental pemphigus can also be induced by Dsg3-hybridoma cell lines." (PMID 37180099, 2023). "Therefore, we speculated that ADAMs might also regulate adhesion of the pemphigus antigens Dsg1 and Dsg3." (PMID 35844545, 2022). "Furthermore, a higher co-localization of Dsg1 with Dsg3 in GL was observed for pemphigus patients." (PMID 35711465, 2022). "Since RTX is approved as a first-line treatment for pemphigus, we assessed whether the number and the isotypes of anti-DSG3 IgG subclasses in sera from patients at the onset of pemphigus might predict the occurrence of relapses under treatment or after treatment withdrawal." (PMID 35371083, 2022). "Therefore, it was proposed that Dsg1 and Dsg3 mediate autoantibody-specific signaling which may contribute to the different clinical phenotypes in pemphigus." (PMID 35634274, 2022). "However, there is evidence also suggesting pemphigus blistering is not solely caused by autoantibody targeting to DSG3 but rather results from intracellular signaling mediated by non-DSGs targeting autoantibodies that leads to shrinkage of cell and apoptosis." (PMID 34206820, 2021). "However, whilst it was shown that anti-Dsg1 and anti-Dsg3 antibodies are pathogenic, the role of most other antibodies for the pathology of pemphigus is not clear." (PMID 34434944, 2021). "However, recent studies suggest that the presence of autoantibodies against DSG1 and DSG3 alone is not sufficient to fully explain the loss of cell-to-cell adhesion observed in pemphigus." (PMID 31275323, 2019). "The clinical improvement was accompanied by a decrease in anti-Dsg1 and anti-Dsg3 titers, as demonstrated by a significant association between the PDAI and antibodies against the Dsg1 and Dsg3, which suggests that these autoantibodies implicate in pathogenesis of the pemphigus." (PMID 26417354, 2015). "Furthermore, a mouse monoclonal antibody directed against the amino-terminal adhesive interface of Dsg3 induces the pemphigus phenotype in mice, and a study using atomic force microscopy revealed that PV IgG can directly inhibit Dsg3-mediated trans-interactions." (PMID 23226536, 2012).
pemphigus (continued). "This CLIA showed strong agreement with IIFT-BIOCHIP, achieving area under the curve (AUC) values of 0.92 for anti-Dsg1/anti-Dsg3 and 0.84 for anti-BP180/anti-BP230 for differentiating pemphigus and BP." (PMID 40661962, 2025). "In the case of coexistence of SLE and PV, ANA are detected; desmoglein 3 is present in the case of pemphigus vulgaris limited to the mucous membranes or DSG3 and DSG1 in the case of pemphigus of the mucous membranes and skin." (PMID 39860415, 2025). "The positive rates of anti-Dsg1, Dsg3, BP180 and BP230 antibodies were 68.5%, 63.0%, 9.3% and 0% in patients with pemphigus, and 1.89%, 0.94%, 76.42% and 37.74% in patients with BP, respectively." (PMID 40661962, 2025). "92.6% of pemphigus patients and 79.25% of BP patients were positive for at least one AIBD autoantibody (Dsg1, Dsg3, BP180, BP230)." (PMID 40661962, 2025). "Our findings revealed good diagnostic value, with AUCs of 0.93 (95%CI: 0.89–0.98) for anti-Dsg1/anti-Dsg3 and 0.87 (95%CI: 0.82–0.92) for anti-BP180/anti-BP230 in differentiating pemphigus and BP, consistent with prior studies." (PMID 40661962, 2025). "Yuan and colleagues recently revealed that autoreactive Dsg1 and Dsg3 specific antibody‐secreting CD19+ B cells and CD138+ plasmablasts are more prevalent in lesional skin compared to healthy skin in pemphigus patients." (PMID 40051023, 2025). "This implies that periodic assessments of anti-Dsg1 IgG, anti-Dsg3 IgG, and DIF can predict relapse in pemphigus." (PMID 40084347, 2025). "A novel fully automated chemiluminescent immunoassay (CLIA) has been developed to quantify autoantibodies specific for desmogleins (Dsg1, Dsg3), BP180, and BP230, key target antigens in pemphigus and bullous pemphigoid." (PMID 40661962, 2025). "The novel CLIA, the first to quantify four major autoimmune blister disease autoantibodies (anti-Dsg1/anti-Dsg3/anti-BP180/anti-BP230) using a single sample tube, offers a simple and time-efficient test for diagnosing and screening pemphigus and BP." (PMID 40661962, 2025). "Risk factors for relapse include high body surface area (BSA) of pemphigus involvement, high body mass index, high severity according to the Pemphigus Disease Area Index (PDAI) at onset, treatment delay, and high anti‐DSG1 and DSG3 titers post‐treatment." (PMID 39460496, 2024). "Risk factors for pemphigus relapse include patients with high PDAI at onset, high BMI, high affected BSA, non‐mucosal pemphigus subtypes, PV, and high DSG1 and DSG3 populations after treatment." (PMID 39460496, 2024). "Pemphigus develops due to the production of anti‐DSG1 and DSG3 antibodies by errant autoreactive B‐cells." (PMID 39460496, 2024). "Monoclonal antibodies (mAbs), developed by immunization of mice with the recombinant mouse Dsg3 ectodomain, such as AK23, or isolated by phage display from active pemphigus patients, are now being extensively used to model PV pathogenesis." (PMID 37180099, 2023). "Quantitation of specific anti-DSG1 and DSG3 antibodies can be achieved with DSG ELISA and facilitates pemphigus sub-typing." (PMID 38074463, 2023). "Based on this distribution pattern of the Dsg3 and Dsg1 proteins, the DCH postulates 3 subtypes of pemphigus: Pemphigus foliaceus (PF), mucosal-limited Pemphigus vulgaris (PV), or mucocutaneous PV." (PMID 36211362, 2022). "Previously, application of a tandem peptide directed against Dsg3 was reported to inhibit p38 MAPK activation and keratin filament retraction both in vitro and in the neonatal mouse model of pemphigus." (PMID 32815159, 2020). "When mice were additionally injected with Dsg3 CAAR T cells, they were protected from induction of experimental pemphigus." (PMID 33505392, 2020). "DSG3 and DSC3/DSG3 pemphigus models only partially responded to therapy, while m-PSL was very efficacious in improving the DSC3 model, as shown by PV Score and DSC3 antibody titer." (PMID 31275323, 2019).